SLC6A11 (solute carrier family 6 member 11)
Description:
Mediates sodium- and chloride-dependent transport of gamma-aminobutyric acid (GABA). Can also mediate transport of beta-alanine and to a lower extent that of taurine and hypotaurine (By similarity).
Synonyms: GAT-3; GAT3; GAT4
Tractability: Small molecule: a high-quality ligand is known; it belongs to a druggable protein family. Antibody: its Gene Ontology location is reachable by antibodies, with high confidence; UniProt places it where antibodies can reach, with medium confidence; UniProt predicts a signal peptide or a membrane-spanning region. PROTAC: ubiquitination databases record sites on it; its protein half-life has been measured; a small molecule that binds it is known.
Target class: SLC superfamily of solute carriers; SLC06 neurotransmitter transporter family; Electrochemical transporter; Transporter
Gene: Protein-coding gene on chromosome 3 (10,816,201 to 10,940,714, forward strand). Ensembl gene ENSG00000132164.
Subcellular location: Cell membrane
Subcellular location (Human Protein Atlas): Nucleoplasm; Vesicles
Pathways (Reactome):
Metabolism: Creatine metabolism
Neuronal System: Reuptake of GABA
Transport of small molecules: SLC-mediated transport of neurotransmitters
Gene Ontology:
Molecular function: gamma-aminobutyric acid:sodium:chloride symporter activity; monocarboxylic acid transmembrane transporter activity; amino acid binding; amino acid:sodium symporter activity; taurine:sodium symporter activity; transmembrane transporter activity
Biological process: monocarboxylic acid transport; amino acid transport; gamma-aminobutyric acid reuptake; neurotransmitter transport; sodium ion transmembrane transport; amino acid transmembrane transport; neurotransmitter uptake; response to xenobiotic stimulus; taurine transmembrane transport
Cellular component: membrane; plasma membrane; GABA-ergic synapse; postsynaptic membrane; presynaptic membrane; synapse
Genetic constraint (gnomAD): Loss-of-function variants: 22 observed, 58.89 expected, observed/expected ratio (o/e) 0.37, 90% interval 0.27 to 0.53. The upper end of that interval is the gene's LOEUF score, 0.53, which puts it in group 2 of 6, group 1 being the genes least tolerant of losing a copy. Missense variants: 507 observed, 731.36 expected, observed/expected ratio (o/e) 0.69, 90% interval 0.64 to 0.75. Synonymous variants: 297 observed, 296.79 expected, observed/expected ratio (o/e) 1, 90% interval 0.91 to 1.1.
Homologues: Orthologues: chimpanzee SLC6A11 (99% identical), macaque SLC6A11 (98% identical), pig SLC6A11 (95% identical), dog SLC6A11 (94% identical), rat Slc6a11 (94% identical), mouse Slc6a11 (94% identical), rabbit SLC6A11 (92% identical), guinea pig SLC6A11 (84% identical), zebrafish slc6a11b (72% identical). Paralogues in human: SLC6A13 (65% identical), SLC6A12 (63% identical), SLC6A6 (58% identical), SLC6A8 (51% identical), SLC6A7 (41% identical), SLC6A5 (41% identical), SLC6A4 (40% identical), SLC6A9 (40% identical), SLC6A2 (39% identical), SLC6A14 (38% identical), SLC6A3 (38% identical), and 6 more.
Diseases named in the same sentence as SLC6A11 in open-access papers:
SLC6A11 is named in the same sentence as 23 diseases in open-access papers, as found by Europe PMC text mining. Sharing a sentence is not in itself a finding about the gene and the disease. The quoted sentences say what the papers report.
depression (3 papers, 2011 to 2016). "The expressions of Hbb-b1 and Nr1d1 are raised, as well as the expressions of Gad1, Mbp and Slc6a11 are decreased in CUMS-induced depression mice, compared to the control mice (p<0.01)." (PMID 27427907, 2016). "The decreased expressions of mRNAs in CUMS-induced depression mice include Slc6a11, Hap1, Gad1, Gad2, Gng4, Slc32a1, Doc2g, Slc32a1, Magel2, Prkcd, Ngfr, Dusp1, Th, Itih3, Cacna2d2, Arc, Mbp, Peg10, Fos, and so on." (PMID 27427907, 2016). "These genes included SBNO2, CEACAM5, AKAP1, UBC, ACTB, UBB, and FOS for schizophrenia; SEC24C, PGLYRP1, ARHGAP4, RPL22, SLC6A11, and SYK for bipolar disorder; and SRRT, PARK2, LILRA4, STK17A, IGFBP2, and NF1 for major depression." (PMID 22373040, 2011).
Doose Syndrome (2 papers, 2020 to 2021).
epilepsy (1 paper, 2023). A brain disorder characterized by episodes of abnormally increased neuronal discharge resulting in transient episodes of sensory or motor neurological dysfunction, or psychic dysfunction. "Thus, in this study, we aimed to discuss the possible connections between SLC6A11, GABRG2, and targeted genetic variation in DRE to provide novel targets and strategies for the treatment of epilepsy in the future." (PMID 37275237, 2023).
multiple sclerosis (1 paper, 2022). A progressive autoimmune disorder affecting the central nervous system resulting in demyelination. "A further four—ATP9A, TMEM232, PHACTR2 and SLC6A11—out of the seven autoimmune genes identified in this study can also be linked to multiple sclerosis development." (PMID 36517845, 2022).
Type 2 Diabetes (1 paper, 2019). "For T2D, this has been demonstrated in studies which identified SLC6A11 in Mexicans by the SIGMA Type 2 Diabetes Consortium46, SGCG in Punjabi Sikhs47, and KCNQ1 in East Asians48,49 as novel risk loci for T2D." (PMID 31324766, 2019).
infection (2 papers, 2012 to 2025). The state of being infected such as from the introduction of a foreign agent such as serum, vaccine, antigenic substance or organism. "Nine down-regulated DEGs were commonly downregulated in response to either Aβ pathology or MA10 infection (Vegfa, Atp1a2, Slc6a11, Gja1, Slc6a11, Gpr37l1, Plpp3, Gstm1, Agt)." (PMID 41497643, 2025).
tumor (2 papers, 2012 to 2024). "Results demonstrated an invariably unmethylated (WNT10B) or methylated (TUB, ALOX12B, SLC6A11) status of the normal samples (data not shown) as compared to the variable levels of methylation observed in tumor cells." (PMID 22950745, 2012).
cancer (1 paper, 2022). A tumor composed of atypical neoplastic, often pleomorphic cells that invade other tissues. "And some identified 3′-UTR piSNV-affected genes, such as SLC6A11, NUDCD2, CTNNA3, RAB3C, and AJAP1, are well-studied cancer/disease related genes with a high deleterious mutation rate." (PMID 35654793, 2022).
neurodevelopmental disorder (1 paper, 2025). A behavioral and cognitive disorder with onset during the developmental period that involves impaired or aberrant development of intellectual, motor, or social functions. "Among these, haploinsufficiency ofSETD5, BRPF1, CRBN, ATG7, SLC6A11, GRM7, and ARPC4has been linked to neurodevelopmental disorders and cognitiveimpairment." (PMID 40995453, 2025).
psychiatric disorder (1 paper, 2021). A disorder characterized by behavioral and/or psychological abnormalities, often accompanied by physical symptoms.
SLC6A11 also shares sentences with these, for which no sentence is quoted: absence seizures (1 paper); age-related hearing loss (1); Alzheimer disease (1); bipolar disorder (1); Cognitive impairment (1); developmental delay (1); infarction (1); neurodegenerative disease (1); Obesity (1); obsessive-compulsive disorder (1); prion disease (1); schizophrenia (1); tobacco use disorder (1).